DACH1 (dachshund family transcription factor 1)
Diseases named in the same sentence as DACH1 in open-access papers (continued):
Sharing a sentence is not in itself a finding about the gene and the disease.
breast carcinoma (continued). "Together, these results suggest that lung-derived FGF2 may influence stemness/plasticity and metastatic behavior of breast cancer cells by inhibiting DACH1 expression." (PMID 38581619, 2024). "Additionally, the IHC staining also demonstrated that S100A8 and S100A9 were negatively correlated with DACH1 expression in breast cancer samples." (PMID 38093319, 2023). "Furthermore, we devised a comprehensive prognostic model that combines S100A8/A9 with DACH1, a widely recognized tumor suppressor in breast cancer, to distinguish breast cancer patients with unfavorable prognoses." (PMID 38093319, 2023). "Here, we analyzed the correlation among S100A8, S100A9, and DACH1 mRNA expression in breast cancer." (PMID 38093319, 2023). "The combination of S100A8/A9 and DACH1 could more effectively differentiate breast cancer patients with poor outcomes." (PMID 38093319, 2023). "Our study showed that DACH1 could repress the breast cancer cell metastasis and invasion by inhibiting the expression of MMP9 at the transcriptional level." (PMID 34772908, 2021). "Our results confirmed the effect of DACH1 on the inhibition of breast cancer metastasis." (PMID 34772908, 2021). "In conclusion, we found a new mechanism that DACH1 could inhibit the metastasis of breast cancer cells by inhibiting the expression of MMP9." (PMID 34772908, 2021). "And this new mechanism of the inhibition of breast cancer metastasis mediated by DACH1 may provide a novel insight into the treatment of breast cancer metastasis." (PMID 34772908, 2021). "It is interesting to mention that four methylation markers (RASGRF1, CPXM1, HOXA10, and DACH1) in circulating cell-free DNA could discriminate cancer from normal with high sensitivity (0.86) and specificity (0.83) in early breast cancer." (PMID 32550045, 2020). "Notably, it has been revealed that DACH1 was expressed in estrogen receptor breast cancer cells and acted as an endogenous inhibitor of estrogen signaling." (PMID 32550045, 2020). "Furthermore, the TGFβ signalling pathway, which has major roles in the EMT, is suppressed by Dach1 via binding to Smad4 in breast cancer tissue, thereby controlling the EMT." (PMID 31405829, 2019). "DACH1 is a tumor suppressor gene in many cancers such as colorectal, oral and breast cancers." (PMID 30261897, 2018). "Knock-down of DACH1 in breast cancer cells MCF-7 and T47D promoted the morphology change from epithelial phenotype to mesenchymal pattern and interfered with cell–cell contact, accompanied by down-regulation of epithelial marker E-cadherin, resulting in cell migration and invasion." (PMID 28659634, 2017). "Altogether, these studies suggested that DACH1 could be a valuable molecular marker for prognosis, thereby detection of DACH1 level is useful for therapeutic stratification of breast cancer patients." (PMID 28659634, 2017). "Furthermore, mice transplanted tumor model indicated that breast cancer cells Met-1 with up-regulation of DACH1 were endowed with remarkably reduced potential of tumorigenesis." (PMID 28659634, 2017). "Besides, DACH1 inhibited breast cancer migration and invasion also via suppressing oncogene function through targeting interleukin-812." (PMID 28659634, 2017). "Besides, previous study has revealed that DACH1 decreased both in breast cancer cell lines and tissues accompanied by relatively high proportion of CSCs18." (PMID 28659634, 2017). "DACH1 was first shown to inhibit TGF-β signaling by binding to SMAD4 in breast cancer." (PMID 27203207, 2016). "Next, we sought to determine whether the epithelial marker E-cadherin has a part in this DACH1-induced morphological change and colony formation observed for these breast cancer cells." (PMID 25775416, 2015). "Taken together, these data indicated that DACH1 may be crucial for breast cancer cells to maintain an epithelial morphology and cell–cell contact." (PMID 25775416, 2015).
breast carcinoma (continued). "DACH1 was expressed in normal breast tissues with reduced expression in breast cancer tissues." (PMID 25775416, 2015). "Strong nuclear DACH1 staining is more prevalent in tubular and lobular breast cancer." (PMID 24392136, 2014). "It is important that expression level of DACH1 can predict survival in breast cancer." (PMID 25322986, 2014). "DACH1 repressed p21CIP1 and induced RAD51, an association found in basal breast cancer." (PMID 23798621, 2013). "Interestingly, DACH1 is also known to suppress ERα in breast cancer cells." (PMID 38581619, 2024). "Besides, accumulating evidence demonstrates that DACH1 acts as a tumor suppressor in multiple types of cancers, including but not limited to breast cancer, non-small cell lung cancer, gastric cancer, esophageal cancer, hepatocellular carcinoma, renal carcinoma, and colorectal cancer." (PMID 38093319, 2023). "Importantly, circulating cell-free DNA-based four methylation markers (RASGRF1, CPXM1, HOXA10, and DACH1) and two parameters (cfDNA concentration and the mean of 12 methylation markers) could detect early breast cancer." (PMID 36750914, 2023). "Collectively, our study indicated that CD44 might be a novel target of DACH1 in breast carcinoma." (PMID 28659634, 2017). "Thus, we concluded that DACH1 might exert inhibitory effects on the development of breast cancer partly by suppression of EMT inducers and CSCs markers, especially CD44." (PMID 28659634, 2017). "Taken together, these data showed that DACH1 could inhibit breast cancer metastasis in our animal model, thus supporting our finding that DACH1 acts as a crucial factor in the suppression of metastasis of breast cancer cells." (PMID 25775416, 2015). "Such speculation was supported by our data, which showed that the expression of E-cadherin paralleled the expression of DACH1 and that DACH1-mediated enhanced transcription of E-cadherin in breast cancer cells ultimately led to the inhibition of EMT in these cells." (PMID 25775416, 2015). "Hopefully, better insights into the regulation of DACH1-mediated repression of cancer metastasis from future investigations may form the basis for designing better therapies that specifically target the metastatic stage of breast cancer." (PMID 25775416, 2015). "To test this, we treated breast cancer cells with recombinant FGF2 protein and observed a dose dependent decrease in DACH1 transcript levels as compared to vehicle control (p≤0.05)." (PMID 38581619, 2024). "We also showed that loss of DACH1 inhibited metastatic outgrowth in the lung suggesting that FGF2 and other soluble factors secreted in the microenvironmental may play a critical role in regulating DACH1 expression and orchestrate metastatic behavior of breast cancer cells." (PMID 38581619, 2024). "To further explore the clinical significance of S100A8/A9 and DACH1 levels in breast cancer, we performed a combined analysis using the IHC staining scores of S100A8, S100A9, and DACH1." (PMID 38093319, 2023). "Contrary to DACH1, EYA2 facilitates proliferation, migration, invasion, and metastasis of breast cancer cells." (PMID 32550045, 2020). "The following survival analyses showed DACH1, EYA2, and SIX1 were predictive biomarkers of prognosis of breast cancer patients." (PMID 32550045, 2020). "Among the 4 genes, RASGRF1 and CPXM1 represented common breast cancer marker, while HOXA10 and DACH1 represented luminal-dominant marker and triple negative dominant marker, respectively." (PMID 32550045, 2020).
breast carcinoma (continued). "Meanwhile, another study focused on luminal breast cancer have revealed that GATA3 is frequently mutated and its levels are significantly elevated, and could mediate the transformation of normal cells into breast cancer through deregulation of BCL2, DACH1 and THSD4." (PMID 32538432, 2020). "Studies have revealed that DACH1 inhibits SNAI1, and TGF‐β‐mediated EMT is involved in breast cancer, which promoted us to explore the possibility that DACH1 regulates EMT in progestin resistance." (PMID 31215145, 2019). "In previous study, we found that DACH1 restrained CXCL8-induced invasion and metastasis of breast cancer through selectively interacting with the AP-1 and NF-κB binding sites of the CXCL8 promoter." (PMID 29636079, 2018). "In this study, 19 public datasets were enrolled to assess the correlation between the mRNA levels of DACH1 and CD44 and the survival performance of breast cancer patients." (PMID 28659634, 2017). "We also carried out IHC staining to assess the protein abundance of DACH1 and CD44 in luminal-type and basal-like breast cancer tissues." (PMID 28659634, 2017). "Our results demonstrated that DACH1 was a promising biomarker predictive of better clinical outcomes, while CD44 was an adverse factor for the survival performance of breast cancer patients." (PMID 28659634, 2017). "In order to assess the prognostic value of DACH1 and CD44 in breast cancer, a meta-analysis enrolling a total of 19 published Gene Expression Omnibus (GEO) databases and including 3574 breast cancer patients was performed." (PMID 28659634, 2017). "Overexpression of DACH1 reduced the levels of CSC and EMT markers in breast cancer cell line and potently inhibited the ability of tumorgenesis in xenograft model." (PMID 28659634, 2017). "In previous studies, we found that SNAI1 cooperates with ERα and DACH1 to regulate E-cadherin expression and EMT in breast cancer cells by binding with the E-box of the E-cadherin promoter." (PMID 29163781, 2017). "In conclusion, this study confirmed that DACH1 and CD44 inversely related in breast cancer, different grade tumors and different subtypes." (PMID 28659634, 2017). "To further evaluate the correlation between DACH1 and CSC markers and EMT inducers in breast cancer, we performed a comprehensive analysis of immunohistochemistry (IHC) staining, publicly available microarray data, RNA profiling and western blot." (PMID 28659634, 2017). "DACH1 was majorly found in nucleus and CD44 was mostly detected on the membrane of breast cancer cells." (PMID 28659634, 2017). "In breast cancer, Zhang reported that miR-217 promotes MCF-7 and MDA-MB-231 cell proliferation via targeting DACH1." (PMID 28437471, 2017). "DACH1 was found to abolish YB-1-induced SNAI1 translation and thus reverse EMT in basal-like breast cancer, an aggressive subtype." (PMID 27203207, 2016). "Taken together, our finding has uncovered another mode of regulation for E-cadherin transcription in breast cancer, one that is based on direct antagonism of the SNAI1 protein by DACH1." (PMID 25775416, 2015). "Based on the observation that DACH1 could maintain an epithelial morphology, increase the expression of epithelial markers E-cadherin, and suppress cell migration and invasion, we speculated that DACH1 might block the transition from epithelial to mesenchymal phenotype in these breast cancer cells." (PMID 25775416, 2015). "DACH1 inhibited the transcriptional activity of SNAI1, leading to the activation of E-cadherin in breast cancer cells." (PMID 25775416, 2015). "Our data did confirm that DACH1 acts as a negative regulator of EMT by showing that DACH1 expression effectively inhibited the cell–cell adhesion and motility of breast cancer cells." (PMID 25775416, 2015). "For example, the paracrine signal repressed by DACH1 in glioma stem cells was FGF2; while DACH1 targets IL-8 in breast cancer cells." (PMID 25322986, 2014).
breast carcinoma (continued). "In this study, we found that breast cancer cells exposed to LCM from TNBC-tumor bearing mice significantly increased acquisition of a stem-like phenotype and significantly decreased expression of a potential tumor suppressor, Dach1." (PMID 38581619, 2024). "DACH1 could decrease the expression of MMP9 and MMP2 in in gastric cancer, so the effect of DACH1 on the expression of MMP9 and MMP2 was examined in breast cancer cells." (PMID 34772908, 2021). "Our previous research has shown that DACH1 had no discernible influence on cell proliferation within 24 h, which indicates that the reduced motility of breast cancer cells with DACH1 overexpression was not due to inhibiting the cell proliferation." (PMID 34772908, 2021). "Of note, DACH1 and VCAN showed obvious upregulation in breast cancer with lymph node metastasis." (PMID 35211507, 2021). "Eventually, we utilized DACH1 (HR = 0.758, P = 0.083), SIX1 (HR = 1.365, P = 0.036), as well as other previously verified molecular factors to construct a predictive model for potential relapse of breast cancer patients." (PMID 32550045, 2020). "Besides, decreased DACH1 and increased EYA2 and SIX1 heralded the poor prognosis of breast cancer patients." (PMID 32550045, 2020). "Our study indicated that DACH1 was inversely correlated with CD44 and CD44 might be a novel target of DACH1 in breast cancer." (PMID 28659634, 2017). "In order to evaluate the expression of DACH1 and CD44 in normal breast and breast malignant tissues, we carried out IHC analysis on two TMAs (BR1502–97 and BR1502-98) with normal breast and human breast cancer tissues." (PMID 28659634, 2017). "This study provided results that expression types of DACH1 and CD44 were opposite in breast cancer." (PMID 28659634, 2017). "DACH1 also regulated the migration and invasiveness of breast cancer cells, a function that appeared to be independent of its general effects on cell proliferation." (PMID 25775416, 2015). "Interestingly, we previously reported that DACH1 attenuated Ras-induced migration, invasion and CXCL8 secretion in breast cancer." (PMID 25788272, 2015). "Taken together, these results demonstrated that DACH1 might have an important role in regulating the expression of epithelial and mesenchymal markers during EMT in breast cancer cells." (PMID 25775416, 2015). "We also analysed the association between DACH1 and E-cadherin levels in SNAI1-positive or -negative breast cancer tissue samples." (PMID 25775416, 2015). "DACH1 inhibits EMT and tumor initiated cells in breast cancer and glioma." (PMID 25788272, 2015). "We also proposed that DACH1 interacted with SNAI1 at the E-box of E-cadherin promoter and inhibited the transcriptional activity of SNAI1, leading to the activation of E-cadherin in breast cancer cells." (PMID 25775416, 2015). "More recently, increased DACH1 expression was reported to correlate with reduced expression of IL-8 and other related chemokines, thus inhibiting cellular migration and invasion in MCF10A breast cancer cells." (PMID 24392136, 2014). "However, the exact molecular mechanisms for the anti-tumor roles of DACH1 in breast carcinoma are still lack of extensive understanding." (PMID 28659634, 2017). "Furthermore, deregulation of BCL2, DACH1 and THSD4 may represent key events accompanying GATA3-mediated transformation of normal cells into breast cancer." (PMID 25410484, 2014). "Besides, it has been verified that DACH1 could suppress epithelial-mesenchymal transition (EMT), migration, metastasis by antagonizing YB-1-mediated transcriptional events, SNAI1-E-cadherin pathway, and IL-8 transcription in breast cancer cells." (PMID 32550045, 2020).
breast carcinoma (continued). "Additionally, ectopic expression of miR-217 directly inhibits DACH1 by binding to its 3′UTR, which not only may exhibit the tumorigenic role of miR-217 in breast cancer, but also suggests an approach for recovering DACH1 expression by diminishing the activation of a particular miRNA." (PMID 27203207, 2016).
lung carcinoma (17 papers, 2014 to 2023). "In a study of lung cancers based on whole-genome sequencing, DACH1 emerged as a biologically significant target of mutation (loss-of-function alterations in particular), and its homozygous deletion has been reported in some glioblastoma multiformes." (PMID 24472434, 2014). "Studies have extensively demonstrated that the down-expression of DACH1 is related to poor prognoses in many tumors, such as BC, prostate cancer, lung cancer, and hepatocellular carcinoma." (PMID 36750914, 2023). "Hsa-miR-6807-3p has been identified to promote glioma tumorigenesis by regulating downstream DACH1 and it can also promote the development of lung cancer through the miR-6807-3p/DKK1 axis." (PMID 35578189, 2022). "Transcriptional repression of IL-8 promoter activity using DACH1 or treatment with IL-8 antagonists can provide a favorable survival for lung cancer patients." (PMID 36185222, 2022). "Bioinformatics analysis and Luciferase reporter assay identified DACH1 as a direct target of miR-217, suggesting that the HOTAIR/miR-217/DACH1 signaling pathway is strongly involved in lung cancer progression." (PMID 33540611, 2021). "In vitro study confirmed that secretion of CXCL1 protein was significantly suppressed by DACH1 in lung cancer cell lines A549 and SKLU-1." (PMID 31998654, 2019). "In comparison with normal tissues, DACH1 protein and mRNA expression level obviously decreased in several tumor tissues, including lung cancer." (PMID 31998654, 2019). "Our previous study has demonstrated that DACH1 overexpression remarkably inhibited the growth of lung cancer in nude mice." (PMID 31998654, 2019). "As previous studies proved that DACH1 was considered as a tumor suppressor in several kinds of cancers including lung cancer and regulated multiple cytokine expression." (PMID 31998654, 2019). "In agreement with previous result, DACH1 transcriptionally downregulates the CXCL8 in NSCLC, and an inverse relationship between CXCL8 and DACH1 was identified in lung cancer cell lines and tumor tissues." (PMID 29636079, 2018). "Based on this observation, we conducted relevance analysis between CXCL8 and DACH1 at mRNA level in lung cancer tissues and cell lines." (PMID 29636079, 2018). "In order to study the clinical relevance of DACH1 expression and lung cancer development, this study enrolled 36 patients diagnosed with lung adenocarcinoma ranged from 45 to 74 years, and the mean age at the time of surgery was 58.0 years." (PMID 26810067, 2016). "In order to determine the alteration of DACH1 expression in lung cancer, we performed Western blotting (WB) and IHC analysis of DACH1 levels between the 36 pairs of lung adenocarcinoma tissues and adjacent non-tumor tissues." (PMID 26810067, 2016). "In conclusion, the present study demonstrates that DACH1 acts as a potential tumor suppressor in lung cancer tissues and cells through the downregulation of PRX3 expression." (PMID 26810067, 2016). "In order to investigate the influence of DACH1 on cell proliferation and invasion, wild-type lung cancer cells and cells infected with DACH1 or empty vectors (NC) were employed in the subsequent studies." (PMID 26810067, 2016). "Recently, several studies focused on the effects of DACH1 on the proliferation and invasion of lung cancer cells." (PMID 26810067, 2016). "The link of DACH1 to lung cancer was initially uncovered by whole-genome and transcriptome sequencing of NSCLC samples." (PMID 25788272, 2015). "A subsequent study in lung cancer has also demonstrated that DACH1 can suppress the secretion of CXCL5, thereby reducing CXCL5-mediated proliferation, migration and invasion." (PMID 26682253, 2015).